BDNF (brain derived neurotrophic factor)
Diseases named in the same sentence as BDNF in open-access papers (continued):
Sharing a sentence is not in itself a finding about the gene and the disease.
Stroke (continued). "As compared to the stroke without intervention, exercise, RIC, and our new rehab strategy, all significantly increased mRNA and protein expressions of SYN, PSD‐95, and BDNF (p < 0.05) at Day 28 of reperfusion." (PMID 37580991, 2023). "BDNF changes in non-PSD patients between seven days and six months post-stroke were also non-significant." (PMID 34141514, 2021). "The evidence suggests that BDNF and APOE loci are involved in recovery from TBI or stroke, but recent GWAS studies in stroke recovery have failed to implicate either." (PMID 33479258, 2021). "In conclusion, this study observed that BDNF serum level has a negative correlation,while serum MDA and 8-OhdG levels have a positive correlation with depressionone-month post-stroke." (PMID 32206197, 2020). "We examined BDNF reactivity in TNF-α+ and IL-β+ cells (not restricted to macrophages) two days after stroke." (PMID 30405724, 2018). "It thus seems likely that excessive levels of cytokines and/or reductions of BDNF, particularly if they persist for extended periods, as well as the balance between these factors, might be keyed in determining whether positive or negative outcomes emerge after stroke." (PMID 23675319, 2013). "9cRA marginally enhanced the expression of BMP7, but not GDNF or BDNF, in the SVZ of stroke rats." (PMID 28674431, 2017). "Infusion of recombinant BDNF into Sprague-Dawley rat neocortex by an implanted osmotic minipump 2.5–14 days before, during, and for 2 days following MCAO reduced infarct volume as measured 2 days after stroke without affecting cerebral blood flow." (PMID 24818146, 2014). "Up-regulated serum and brain pro-inflammatory cytokines elicited by TBI or stroke were attenuated by treatment with rhEPO, although EPO administration enhanced BDNF up-regulation elicited by cerebral ischemia, but did not prevent inflammatory gene up-regulation (e.g., IL-1β, IL-6, TNF-α)." (PMID 23675319, 2013). "For example, previous work has revealed increased motor recovery following experimental stroke in rats following administration of the BDNF AMPA PAM CX1837 as compared to the non-BDNF AMPA PAM CX1739, suggesting that BDNF-inducing AMPA PAMs may have superior therapeutic potential." (PMID 24380895, 2013).
schizophrenia (605 papers, 2007 to 2026). A major psychotic disorder characterized by abnormalities in the perception or expression of reality. "Another study found that the BDNF genetic polymorphism rs6265 (G/A) increased susceptibility to schizophrenia, and BDNF Val66Met genetic polymorphism was associated with some aspects of cognitive function, such as language performance." (PMID 40082848, 2025). "Our findings indicated that NGF-β and BDNF levels were altered in chronic schizophrenia and were associated with clinical symptoms and vitamin D metabolism." (PMID 40082848, 2025). "Three pathological states (AD, ALS and schizophrenia), have consistently implicated reductions in CNS BDNF levels in CSF, which suggests some form of dysregulation of BDNF in the CNS." (PMID 40362507, 2025). "Our findings demonstrated decreased NGF-β and BDNF levels in chronic schizophrenia patients, suggesting their potential association with the risk of the disorder." (PMID 40082848, 2025). "The severity of psychopathology in patients with schizophrenia seems associated with higher levels of IL-1β and lower levels of BDNF." (PMID 41010622, 2025). "HERVs contribute to schizophrenia pathogenesis through neuroinflammatory pathways, neurotoxicity, and the dysregulation of risk genes (e.g., BDNF, DISC1, PRODH) via epigenetic and transcriptional mechanisms." (PMID 41200560, 2025). "BDNF has been implicated in several neuropsychiatric conditions such as schizophrenia and anxio-depressive disorders, as well as in pain states." (PMID 40214430, 2025). "Most studies indicate that schizophrenia is associated with cognitive impairment, and serum or plasma BDNF levels in these patients are lower than those in healthy control groups." (PMID 40896216, 2025). "Individual SNP alleles of genes involved in the regulation of neuroimmune interactions have been proved to be related to schizophrenia, including the brain-derived neurotrophic factor (BDNF) gene association with clinical manifestations of schizophrenia." (PMID 40416497, 2025). "The correlations between NGF-β levels and negative symptoms, as well as 1,25(OH)2D levels, along with the association between BDNF and language deficits, highlighted the significant role of these neurotrophic factors in the pathophysiology of schizophrenia." (PMID 40082848, 2025). "In schizophrenia, decreased BDNF levels have been consistently associated with cognitive deficits and negative symptoms." (PMID 41169352, 2025). "A reduction in BDNF is positively associated with the severity of schizophrenia and cognitive decline." (PMID 41007810, 2025). "Overall, these results indicated distinct roles for BDNF and CREB in the cognitive and psychopathological profiles of schizophrenia, with BDNF more closely linked to executive function and CREB more associated with memory capabilities." (PMID 40534913, 2025). "Alterations in BDNF signaling, which regulates synaptic function via tropomyosin-related kinase B receptors (TrkB), are implicated in schizophrenia alongside NMDA receptor hypofunction." (PMID 39408997, 2024). "In 2008, Pillai A examined the possibility that the aberrant expression of the GF signaling regulator SPRY2 was linked to alterations in BDNF mRNA levels in schizophrenia." (PMID 39456824, 2024). "A robust link has been established between the BDNF Val66Met polymorphism and body mass index (BMI) among chronically ill and medicated male schizophrenia patients." (PMID 38988887, 2024). "Converging evidence from animal and human studies also indicate this BDNF gene polymorphism as a predictor for clinical presentation in schizophrenia." (PMID 40656087, 2024). "In a Chinese population, the occurrence of the dinucleotide polymorphism (GT)n in BDNF gene was found to correlate with early manifestation of schizophrenia and sensitivity to chlorpromazine treatment." (PMID 38646100, 2024).
schizophrenia (continued). "Consistent with this evidence, impairment and dysregulated expression of the Sonic Hh and alterations in BDNF and astrocytes have been associated with various neurodevelopmental disorders, including schizophrenia." (PMID 38920990, 2024). "The relationship between the BDNF-rs6265 genotype and weight variation in patients with schizophrenia, along with the underlying mechanisms, remains to be fully elucidated." (PMID 38988887, 2024). "Increased levels of 5mC and 5hmC in the BDNF promoter reduced the binding of GADD45b protein in the associated chromatin regulatory region and further reduced transcription levels in schizophrenia patients." (PMID 38203806, 2024). "The reduction in BDNF levels in schizophrenia is associated with a decrease in neuroplasticity, meaning a lesser ability to form and reorganize synaptic connections in response to new information or experiences." (PMID 38673018, 2024). "Among Asians, the proportion of Met allele carriers of BDNF gene (41%) is significantly higher than that of Caucasians (18%), and Met allele is a risk factor for schizophrenia." (PMID 39886050, 2024). "A cell-type-specific EWAS study of neonatal blood from individuals who developed schizophrenia later in life strongly supported the involvement of aberrant methylation in B-cells and the gene BDNF in schizophrenia susceptibility." (PMID 38532012, 2024). "Contemporary research has increasingly pointed toward BDNF Val66Met polymorphism as playing a critical role in weight changing during the pathogenesis of schizophrenia." (PMID 38988887, 2024). "Excessive plasma BDNF concentrations are linked to betterment intellectual performance in schizophrenia individuals." (PMID 37287291, 2024). "The pathophysiology of some neurodegenerative diseases, including Alzheimer’s, Parkinson’s, Schizophrenia, and Huntington’s, has been linked to BDNF." (PMID 37287291, 2024). "BDNF is involved in the regulation of neurodevelopment, neuroprotection, synaptic plasticity, learning and memory, and studies have shown that decreased BDNF levels are associated with impaired cognition in schizophrenia." (PMID 38680078, 2024). "The results from studies investigating the BDNF rs6265 gene variant and its relationship to the onset of schizophrenia were inconclusive." (PMID 37626739, 2023). "In patients with schizophrenia, a decrease in BDNF signaling has been proposed as a causal effect of neuropil retraction, leading to hippocampal reduction." (PMID 38130289, 2023). "BDNF protein is highly expressed in the brain regions implicated in schizophrenia, such as the prefrontal cortex, parietal cortex, and hippocampus." (PMID 37189402, 2023). "Apart from this, schizophrenia is also associated with reduction of certain neurotropic peptides, such as brain-derived neurotrophic factor (BDNF) that helps in the neurogenesis and formation of synapses for memory, learning, and executive functioning." (PMID 37602139, 2023). "A recent meta-analysis provided further evidence of the associations between brain volume alterations in schizophrenia and BDNF peripheral levels." (PMID 37445746, 2023). "As is known, BDNF deficiencies play a role in the etiology of schizophrenia due to its fundamental involvement in brain function." (PMID 37685795, 2023). "This cluster discusses mainly the role of BDNF polymorphism in the pathogenesis and risk of schizophrenia." (PMID 37077958, 2023). "At the transcriptional level, multiple studies have shown that schizophrenia is associated with specific BDNF promoters." (PMID 37189402, 2023). "This was the first scientific work indexed in the Scopus database to deal with the BDNF polymorphism as the possible candidate gene for schizophrenia." (PMID 37077958, 2023). "These keywords indicate that the green cluster has publications that focus on BDNF polymorphism associated with smoking/nicotine in schizophrenia as well as functional polymorphisms of other genes such as dopamine, drd3 and COMT." (PMID 37077958, 2023).
schizophrenia (continued). "Clinical studies have shown a causal link between low BDNF levels and cognitive decline in the elderly, schizophrenia, and Rett syndrome." (PMID 37887089, 2023). "The study found that higher BDNF levels were associated with lower depressive symptoms in schizophrenia." (PMID 36979300, 2023). "The receiver operating characteristic (ROC) curve analysis indicated that BDNF had a diagnostic power in differentiating between patients with schizophrenia and methamphetamine addiction." (PMID 37520481, 2023). "Age of onset has also been associated with the BDNF Val66Met gene polymorphism, which is related to poorer cognitive performance in schizophrenia." (PMID 37371989, 2023). "BDNF has been implicated in the mechanism of action of various antipsychotic medications used to treat schizophrenia." (PMID 37109038, 2023). "These keywords indicate that the yellow cluster has publications that focus on the role of BDNF polymorphism as a biomarker in the pathogenesis of schizophrenia and bipolar disorders." (PMID 37077958, 2023). "In human subjects, low peripheral BDNF levels are associated with a reduction in hippocampal volume at the onset of schizophrenia." (PMID 37445746, 2023). "Their studies addressed a variety of themes which were related to BDNF and smoking, antipsychotic drugs, symptoms of schizophrenia, risk of schizophrenia, and cognition." (PMID 37077958, 2023). "The original and review articles about BDNF and its TrkB receptor, BDNF polymorphism and its role as cognitive markers, and therapeutic response in patients with schizophrenia make up the remaining top cited documents." (PMID 37077958, 2023). "Here we performed a systematic search in Pubmed, Embase, and Web of Science databases with the search terms: (BDNF gene polymorphism) AND (schizophrenia) for articles published in the last 5 years." (PMID 37886115, 2023). "The study revealed that individuals affected by schizophrenia and carrying the minor allele of rs6265 (AG/AA) showed significantly lower BDNF levels compared to those who were homozygous for the standard G allele." (PMID 37763162, 2023). "Recent years have seen an increase in interest in research on pertinent topics, such as factors that alter BDNF levels or are linked to BDNF dysfunction in schizophrenia, cognition in schizophrenia, and animal models of the disease." (PMID 37077958, 2023). "Further studies indicate that ERVWE1 increases the expression of schizophrenia risk genes, such as Brain derived neurotrophic factor (BDNF) and Cytoplasmic polyadenylation element binding protein 1(CPEB1)." (PMID 37990254, 2023). "Altogether, our findings suggest that an increased BDNF is associated with a favorable outcome of antipsychotic treatment in schizophrenia patients." (PMID 37485797, 2023). "Specific alleles or SNPs in the brain-derived neurotrophic factor (BDNF) gene have possible neurobiological impacts on the etiology of schizophrenia." (PMID 36817247, 2022). "Taken together, these results indicate that DTNBP1 plays several important roles in regulating inhibitory transmission and pathogenic mechanisms of schizophrenia, at least in part via BDNF secretion." (PMID 35815020, 2022). "According to previous studies, BDNF is implicated in the pathophysiology of schizophrenia and is associated with schizophrenia-related phenotypes." (PMID 35757201, 2022). "Specifically, gained DA‐peaks after BDNF stimulation significantly overlapped with inherited risk loci for bipolar disorder (BD), Schizophrenia (SCZ), intelligence, attention deficit hyperactivity disorder (ADHD), and neuroticism." (PMID 35996956, 2022). "According to an earlier study, the BDNF Val66Met polymorphism has been reported to affect the intensity of depressive symptoms in patients with schizophrenia." (PMID 35757201, 2022). "Serum BDNF levels in untreated patients with schizophrenia are decreased and associated with cognitive impairment." (PMID 36387009, 2022).
schizophrenia (continued). "In this study we sought to investigate the association between BDNF serum levels of patients with schizophrenia and schizoaffective disorder with various demographic, clinical, treatment-related, and genetic factors." (PMID 36552127, 2022). "BDNF rs6265 (Val66Met) is one of the main candidate genes in major depression and in schizophrenia, and it has been implicated in cognitive deficits exhibited by the patients." (PMID 35407454, 2022). "To further clarify the role of BDNF and MMP-9 genes as risk alleles or regulators of schizophrenia, we carried out this case-control association study between BDNF rs6265 and MMP-9 rs3918242 SNPs." (PMID 36325525, 2022). "Although several studies have attempted to establish various cytokines as markers for schizophrenia (such as protein-C Reactive and BDNF), there were always deficiencies when applying these markers in the clinical practice." (PMID 36138890, 2022). "Dysbindin-1 (DTNBP1) and brain-derived neurotrophic factor (BDNF) are both genetic factors associated with schizophrenia." (PMID 35815020, 2022). "In the prefrontal cortex of patients with schizophrenia, downregulation of neuropeptide Y and somatostatin mRNA values are associated with increased miR-195 levels and decreased BDNF expression." (PMID 35916975, 2022). "The same group, in a separate publication, addresses patients with schizophrenia specifically on aripiprazole treatment, finding an association between BDNF levels and the cognitive domains of memory and verbal learning, verbal fluency, and executive function." (PMID 34220575, 2021). "Changes in BDNF expression and Val66Met (rs6562) polymorphism are involved in the pathogenesis of schizophrenia." (PMID 35194435, 2021). "Our current finding of an association between decreased BDNF protein level and multiple reduced cognitive performances in schizophrenia is in line with previous clinical studies done by both ourselves and others." (PMID 33558459, 2021). "BDNF polymorphic variants have been associated with depressive, bipolar, and schizophrenia diseases." (PMID 33809805, 2021). "The effects of the BDNF Val66Met polymorphism on cognition were extensively documented in schizophrenia and healthy individuals." (PMID 34025476, 2021). "It should be noted that BDNF has been investigated as a diagnostic or prognostic biomarker in various psychiatric pathologies, including schizophrenia, but also depression, bipolar disorder, as well as anxiety disorders." (PMID 34220575, 2021). "The molecular pathways involved in schizophrenia form complex and interconnected networks, where BDNF is one of the points where different risk factors converge." (PMID 34220575, 2021). "A growing number of studies have shown that brain-derived neurotrophic factor (BDNF) is associated with weight gain during antipsychotic treatment in schizophrenia patients." (PMID 34482368, 2021). "A recent meta-analysis showed that schizophrenia is associated with reduced BDNF with a medium effect size (Hedges g = −0.458, p < 0.004), and that these effects are not influenced by the drug state of the patients." (PMID 34831151, 2021). "Instead, one possibility is that elevated miR-195 is associated with schizophrenia-related genetic abnormalities, which then suppresses BDNF production." (PMID 33558459, 2021). "Brain-derived neurotrophic factor (BDNF) is also implicated in schizophrenia, and expression is regulated by NMDA-R activity, suggesting a functional link." (PMID 34054433, 2021). "Brain Derived Neurotrophic Factor (BDNF) has been linked to cognitive symptoms of schizophrenia, which has been documented in previous reviews by several authors." (PMID 34220575, 2021). "A recent meta-analysis demonstrated that peripheral BDNF levels in serum and plasma were moderately reduced in patients with schizophrenia compared with controls and that this decrease was associated with disease duration." (PMID 34393855, 2021).